LEP (leptin)
Diseases named in the same sentence as LEP in open-access papers (continued):
Sharing a sentence is not in itself a finding about the gene and the disease.
metabolic syndrome (continued). "The aim of this study was to evaluate the effect of soy consumption on serum leptin levels in postmenopausal women with metabolic syndrome." (PMID 21526104, 2010). "Dietary nutrient and vegetable intake, weight, height, leptin, metabolic syndrome clinical characteristics and related markers of endothelial and cardiovascular health were measured at baseline, 6-, and 12-weeks." (PMID 20178625, 2010). "Because in patients with the metabolic syndrome plasma leptin increases progresssively other the long period of time, gradually increasing leptin dosage seems to be a more physiologically relevant approach." (PMID 21286276, 2010). "We demonstrate that, in this group of obese children with metabolic syndrome, previously undiagnosed SDB was associated with increased SNSA and higher leptin levels and that treating SDB with CPAP was associated with a decrease in leptin levels." (PMID 18762497, 2008). "As evidence that leptin replacement was beneficial to the patient, we documented resolution of hypertension, dyslipidemia and hyperinsulinemia, in the context of decrease in food intake and weight loss." (PMID 18769731, 2008). "The significance of this comparison is gain insights into ethnic variation in leptin physiology and to provide a greater understanding of the etiology of metabolic syndrome among Native American groups." (PMID 16942616, 2006). "The aim of this study is to establish interactions between the GLP-1 plasma levels and metabolic syndrome clusters and adipokines profile (leptin, adiponectin, resistin) and proinflammatory cytokines (TNFα, IL-6, IL1β, IL-17) in diabetic subjects with or without MAFLD." (PMID 41683648, 2026). "The purple cluster represents a basic theme, emphasizing mature adipokine networks wherein bariatric surgery reinstates the adiponectin/leptin equilibrium, and combinatorial biomarkers (adiponectin/leptin ratio + HOMA-IR) attain enhanced diagnostic precision for predicting metabolic syndrome." (PMID 40868109, 2025). "The observed associations were independent of BMI and metabolic syndrome, highlighting leptin’s potential role in refining MASLD risk stratification." (PMID 40956476, 2025). "HFD-fed mice exhibited increased fasting glucose, impaired glucose and insulin tolerance, dyslipidemia, elevated leptin, β-amylase, hepatic mitochondrial oxidative stress, and liver enzymes, alongside decreased fasting insulin, β-cell activity, adiponectin, and islet insulin secretion." (PMID 40726918, 2025). "The method by which metabolic syndrome impacts lung function could be related to increases in pro-inflammatory cytokines, with contributions from elevated insulin, dyslipidemia, and leptin." (PMID 39714726, 2025). "Four weeks were sufficient to induce metabolic changes (reflected e.g. by elevated leptin levels) without causing excessive metabolic syndrome." (PMID 40018036, 2025). "Here, we demonstrate that SQ injection of V7-LEP at a low dose of 4×1010 vg per mouse restored circulating leptin levels comparable to IP injection of V7 vector or IP injection of Rec2/dual cassette vector and normalized the metabolic syndromes in ob/ob mice." (PMID 40709262, 2025). "Several studies indicate that leptin may serve as a key connection between central obesity, hypertension, and metabolic syndrome (MetS)." (PMID 39861488, 2025). "Therefore, it is of interest toevaluate the predictive usefulness of leptin levels for identifying individuals with metabolic syndrome as well as the relationshipbetween leptin and metabolic syndrome and cardiovascular disease risk." (PMID 40255297, 2025). "Gender, BMI, and the presence of metabolic syndrome affect leptin concentrations, and IL-6 may be influenced by immunosuppressive treatments like hydroxychloroquine." (PMID 40283183, 2025). "Thus, monitoring of leptin levels among individuals having metabolic syndrome with andwithout hypothyroidism is relevant." (PMID 40255297, 2025).
metabolic syndrome (continued). "Elevated leptin concentrations in individuals with metabolic syndrome may further exacerbate leptin resistance, contributing to weight gain and impaired glucose metabolism." (PMID 40863890, 2025). "Leptin produced by EAT in metabolic syndrome fosters mitochondrial oxidative stress and dysfunction, initiates apoptosis via mitochondrial pathways, and diminishes cardiomyoblast cell viability through activation of the PKC/NADPH oxidase/reactive oxygen species (ROS) pathway." (PMID 40943899, 2025). "The high leptin group demonstrated substantially worse metabolic parameters across all domains, including glycemic control, lipid profiles, and blood pressure, resulting in higher metabolic syndrome prevalence (91% vs. 84%, p = 0.008)." (PMID 40956476, 2025). "In fact, the leptin-adiponectin axis may contribute to increased inflammation and oxidative stress in individuals with metabolic syndrome." (PMID 38256185, 2024). "The correlation between leptin and WC suggests that visceral fat accumulation may be a driving factor in the development of metabolic syndrome, emphasizing the importance of targeted interventions focused on reducing abdominal obesity in children." (PMID 39771030, 2024). "However, an earlier study investigated the effect of Ramadan fasting on leptin and metabolic syndrome components in T2D patients and revealed significant increase in leptin post Ramadan fasting." (PMID 38172970, 2024). "Leptin plays an important role in the pathophysiology of metabolic syndrome." (PMID 39684379, 2024). "Feeding newborn mice with mature milk instead of colostrum resulted in significant growth retardation associated with the biological features of chronic undernutrition, such as low leptin levels, dyslipidemia, systemic inflammation, and growth hormone resistance." (PMID 39068488, 2024). "Therefore, this concern has motivated us to examine the association between circulating leptin, adiponectin, and GGT and metabolic syndrome in school-aged children from Northeast Mexico." (PMID 39771030, 2024). "It was associated with waist circumference, body mass index, C-peptide and leptin, but also with high blood pressure and dyslipidemia, which could explain its importance in both effects." (PMID 36984813, 2023). "These conventional (age and dyslipidemia) and non-conventional (increased inflammatory markers and leptin) risk factors promote cardiovascular (CV) diseases in the general population as well as in hypopituitary patients like those with SS." (PMID 36742387, 2023). "There are several factors that influence and help in leptin resistance, such as failure to transport leptin across the blood-brain barrier, endoplasmic reticulum stress, reduced hypothalamic signaling, dyslipidemia and genetic variations of leptin and its receptors." (PMID 38015889, 2023). "Besides the ability to regulate metabolic syndrome, including lowering glucose and lipid synthesis, leptin is one of the mediators responsible for the inflammatory state." (PMID 36925956, 2023). "Moreover, curcumin, a lipophilic polyphenol derived from the spice turmeric, which reduces weight, leptin, and leptin levels in patients with metabolic syndrome and related disorders, can inhibit Cdc42 activity." (PMID 38068822, 2023). "In this context, HIT has been shown to induce positive modulation (decrease in inflammatory adipokines such as resistin, leptin and ghrelin, and increase the anti-inflammatory cytokines such as adiponectin) of adipokine profiles in postmenopausal women with metabolic syndrome." (PMID 37576981, 2023). "This might reflect the relevant function of CEA and leptin in the metabolic abnormality diagnostics of PanNENs and deserves further evaluation to increase knowledge about the metabolic syndrome in PanNENs." (PMID 37190276, 2023).
metabolic syndrome (continued). "Our findings suggest that an impairment of the A/L ratio (as seen in metabolic syndrome) in the first trimester is characteristic of PE, while aberrant fetal growth in PE is not dependent on insulin sensitivity, but rather on leptin-associated pathways." (PMID 36676079, 2023). "For four tested variables, VAI, IL-13, adiponectin and leptin AUC was low, which did not render these factors valuable as diagnostic indicators of the metabolic syndrome in our group." (PMID 36596839, 2023). "MetS is characterized by numerous metabolic dysregulations, including insulin resistance, leptin resistance, dysregulated hypothalamus—hypophysis—suprarenal gland axis function, atherogenic dyslipidemia, vascular calcification, central obesity, mitochondrial dysfunction, and altered blood pressure." (PMID 37179826, 2023). "Additionally, a study conducted in young populations found a relationship between serum leptin and its soluble binding protein levels on one hand with measures of adiposity and metabolic syndrome score on the other hand." (PMID 36950695, 2023). "Leptin was positively correlated with all markers (except glucose and dyslipidemia)." (PMID 36355134, 2022). "Furthermore, leptin improves dyslipidemia via activation of 5′-adenosine-monophosphate-activated protein kinase (AMPK), which increases fatty acid oxidation in skeletal muscle." (PMID 35056647, 2022). "Lean participants were also more likely to have lower circulating concentrations of biomarkers of the metabolic syndrome such as leptin (660.9 [174.5–1993.1] pg/ml vs 3988.0 [1336.0–6595.0] pg/ml, p<0.001), and uric acid (246.5 [205.0–290.6] μmol/l vs 289.0 [234.0–347.0] μmol/l, p<0.001)." (PMID 35138411, 2022). "Second, night shift work evokes a decrease in leptin level at night as well as an imbalance in energy metabolism, resulting in night shift workers being more likely to be obese and develop the metabolic syndrome." (PMID 35702390, 2022). "In our study, including overweight or obese persons with at least one criterion of the metabolic syndrome, median baseline serum leptin concentrations of 18.0 μg/L [12.2; 25.5] were measured in females and 6.6 μg/L [4.0; 9.7] in males with tending higher levels in those with prediabetes." (PMID 35745267, 2022). "As an inhibitor of leptin and insulin signaling, increased muscular SOCS3 expression has been suggested as a major contributor to mitochondrial dysfunction, impaired fatty acid oxidation, as associated with aging, metabolic syndrome, and inflammation." (PMID 35151349, 2022). "Moreover, several adipokines such as adiponectin, leptin, and visfatin were evaluated in fatty liver disease and metabolic syndrome." (PMID 35042855, 2022). "In addition, group B (HOMA-IR ≥ 2.5) had significantly more preoperative biomarker abnormalities (other than dyslipidemia) than group A, including leptin, ghrelin, PYY, insulin, RBP4, and LGr." (PMID 36203073, 2022). "It has been suggested that in ESRD patients, high leptin concentrations might be a consequence of metabolic syndrome, which is highly prevalent in ESRD." (PMID 36289903, 2022). "However, PTH, in addition to BMI, insulin and metabolic syndrome score, was found to be an independent predictor of leptin values with both, PTH and leptin, correlating positively in patients at different CKD stages." (PMID 36289903, 2022). "Body weight and fat mass were lower in Mas-ko compared to wt mice, which is on the one hand the opposite of other findings of the same group showing higher body weight and fat mass, as well as dyslipidemia and higher levels of insulin and leptin in Mas-ko mice." (PMID 35431918, 2022). "Simvastatin treats obese asthma by improving dyslipidemia and decreasing leptin level." (PMID 36051916, 2022). "One study reported that LFN decreased leptin levels in mice with dyslipidemia and lipodystrophy." (PMID 34721412, 2021).
metabolic syndrome (continued). "In a subsample of European children forming part of the IDEFICS study, the highest levels of leptin were associated with metabolic syndrome, regardless of body mass." (PMID 33665176, 2021). "In conclusion, these findings suggest that some substances like leptin may involve in the crosstalk between metabolic syndrome and hyperuricaemia." (PMID 34335246, 2021). "The VMH leptin resistance and noradrenergic hyperactivity that each induce the metabolic syndrome in animals fed regular chow (as in the present study) occur without any change in food consumption (as in the present study) and result from major changes in energy expenditure/utilization processes." (PMID 33485386, 2021). "Accordingly, in the present study, we observed a decrease in metabolic syndrome‐related outcomes, such as body weight gain, adiposity, gene expression of inflammatory markers and leptin availability, in HFD‐CAS + ABX mice relative to HFD‐CAS non‐treated counterparts, at both timepoints." (PMID 34057306, 2021). "Furthermore, we should mention the fact that, in men, the leptin/ghrelin ratio had a very good discriminatory capacity for metabolic syndrome (AUROC = 0.923)." (PMID 34829886, 2021). "Previous evidence supports our findings by suggesting that adiponectin, leptin, and their ratio might be useful prognostic markers of metabolic syndrome in schizophrenia." (PMID 34873143, 2021). "Leptin is also considered an important biomarker of metabolic syndrome." (PMID 33842335, 2021). "Moreover, after the administration of vaspin, mRNA expression levels of genes associated with metabolic syndrome (MetS) (GLUT4, resistin, adiponectin and leptin) returned to normal levels in obese rats’ WAT." (PMID 34359881, 2021). "Indeed, for SM C16:1, direct associations were observed with total and HDL cholesterol, leptin, and adiponectin and inverse associations with total cholesterol/HDL cholesterol ratio, triglycerides, glucose, and number of criteria for metabolic syndrome." (PMID 34301304, 2021). "Consistent with this explanation, we confirmed the markers related to dyslipidemia (e.g., PPARγ and leptin) in oleic and palmitic acid (OAPA) and lipopolysaccharide (LPS) treated-HUVECs for mimicking atherosclerosis of artery as well as ABCA1 and its target miRNAs." (PMID 34440128, 2021). "Dyslipidemia in pregnant women could affect birth weight by increasing leptin levels in cord blood, and then influencing the physical development of young children." (PMID 34684402, 2021). "Thus, low concentrations of IL‐38 are found in subjects with metabolic syndrome with high hsCRP and leptin." (PMID 33125159, 2021). "Furthermore, metabolic syndrome and the resulting insulin and leptin resistance and hyperglycaemia have pro-inflammatory effects with profound consequences on the BBB." (PMID 33322180, 2020). "Therefore, defects in leptin action, which occur in a state of hepatic leptin resistance, impair hepatic function and lead to hyperglycemia, hyperinsulinemia, and dyslipidemia (Frühbeck and Nutr, 2002)." (PMID 33210603, 2020). "Various studies have proposed leptin as a predictive marker for metabolic syndrome." (PMID 33489600, 2020). "In conclusion, our results indicate that adiponectin and leptin may play a role in the pathophysiology of metabolic syndrome in patients with schizophrenia." (PMID 33066473, 2020). "In addition, serum leptin in patients with multiple metabolic syndromes was significantly higher than in age-matched healthy men (6.7 vs. 4.6 ng/mL, respectively;)." (PMID 33114326, 2020). "The relevance of endogenous leptin in lipid homeostasis is beyond any doubt since lack of leptin is associated with dyslipidemia and reversal of this alteration is more easily accomplished following leptin replacement than with restricted feeding." (PMID 33316927, 2020). "Significant correlation of leptin levels with metabolic syndrome and thus as a biomarker for increased risk of AMI has not been studied in Pakistan yet." (PMID 33489600, 2020).
metabolic syndrome (continued). "Furthermore, patients with SS who also have metabolic syndrome have increased serum levels of leptin and IL-1β." (PMID 32370746, 2020). "Indeed, summarized evidence suggests that optimal regulation of adipokine markers such as adiponectin and leptin is crucial for the beneficial effects of CoQ10 in attenuating oxidative stress and inflammation in conditions on metabolic syndrome." (PMID 32375340, 2020). "The adipokines leptin, adiponectin, tumor necrosis factor-alpha (TNF-α), and interleukin 6 (IL-6) might be associated with metabolic syndrome (MetS) in patients with schizophrenia." (PMID 33066473, 2020). "In humans, switching to an ω-3 FA-rich diet reduces the serum levels of IL-1β and TNF-α, and increasing evidence suggests that dietary supplementation with ω-3 polyunsaturated fatty acids (PUFAs) can ameliorate metabolic syndrome and modulate circulating levels of leptin and adiponectin." (PMID 32295649, 2020). "Moreover, oral simvastatin treatment abolished the higher leptin expression in RVLM, pointing to a permissive role of dyslipidemia in brain uptake of leptin." (PMID 32446297, 2020). "Likewise, many of the metabolic, cancer and liver-related complications of the metabolic syndrome remain to be assessed and are necessary to better understand the mechanistic basis of leptin in this disease." (PMID 33316927, 2020). "Intra-abdominal fat also secretes adipocytokines, such as leptin, adiponectin, resistin, and interleukins (IL-1 and IL-6), which act as energy regulators and inflammatory markers and are thus correlated strongly with metabolic syndrome." (PMID 32309767, 2020). "The other possible cause of HFD induced increased body weights, hyperglycemia and dyslipidemia in the current study is the reduction of leptin, adiponectin and UCP1 protein expression, which play important roles in the regulation of food intake, insulin sensitivity and energy metabolism." (PMID 32197395, 2020). "However, the specific neurons that regulate anti-dyslipidemia effects of leptin remain unidentified." (PMID 33071988, 2020). "Thus, the strong relationship between leptin and metabolic syndrome is established after menopause, suggesting a sex-specific leptin effect on cardiometabolic physiology, with a possible interaction between leptin and female sex hormones." (PMID 33114326, 2020). "Perry and her colleagues propose that anti-dyslipidemia actions of leptin are mediated by the HPA-axis because the infusion of corticosterone reverses leptin-induced improvements on aberrant blood FFAs and ketone bodies as well as hyperglycemia in streptozocin (STZ)-administered diabetic rats." (PMID 33071988, 2020). "This study aimed to evaluate the association between serum vitamin D levels and nonalcoholic fatty liver disease (NAFLD) parameters, such as metabolic syndrome (MS), inflammatory cytokines (tumor necrosis factor, high sensitive C-reactive protein) and adipokines (adiponectin, leptin)." (PMID 31311491, 2019). "Indeed, hepatic CB1 receptor is involved in development of diet-induced steatosis, dyslipidemia, and insulin and leptin resistance." (PMID 31121839, 2019). "In addition, this animal model of metabolic syndrome is characterized by increased leptin and triglycerides levels, but lower adiponectin and normal insulin levels." (PMID 31131281, 2019). "Rats fed a diet with increased content of fructose, sucrose, and saturated and trans fatty acids developed signs of metabolic syndrome in humans, especially abdominal obesity, hypertension, impaired glucose and leptin, dyslipidemia, and diminished cardiac function." (PMID 31336561, 2019). "However, the liver-specific CB1 knockout mice showed less steatosis, hyperglycemia, dyslipidemia, and insulin and leptin resistance compared to wild-type mice fed with a HFD." (PMID 31121839, 2019).